CCL20 (C-C motif chemokine ligand 20)
Diseases named in the same sentence as CCL20 in open-access papers (continued):
Sharing a sentence is not in itself a finding about the gene and the disease.
tumor (continued). "As a result, we found that FDPS knockdown significantly reduced CCL20 protein expression in subcutaneous xenograft model, while overexpression of FDPS remarkably promoted CCL20 protein levels in syngeneic tumour tissues." (PMID 32596949, 2020). "The expression level of CCL20 is significantly higher in tumor tissues than in normal control tissues, while CCL20 expression in tissues is positively correlated with Th17 number." (PMID 32707869, 2020). "Nine chemokines were detected in EBNA1+ tumor cells, and the results showed CCL20 and CCL22 overexpressed." (PMID 32573058, 2020). "One study has shown that high CCR6 expression by circulatory Treg and directional migration toward CCL20 promote Treg migration into tumor tissue and that intratumoral CCL20 concentration and tumor-infiltrating Treg number are positively correlated." (PMID 32707869, 2020). "Immune cell infiltration into tumor tissues has been one of the most important effects of CCL20 on the TME." (PMID 32707869, 2020). "In HNSCC, significantly increased CCL20 expression was observed in primary tumour tissue compared with normal mucosa." (PMID 32601464, 2020). "The majority of tumor-associated macrophages (TAMs) expressed proinflammatory cytokine/chemokine genes, such as IL1B, CCL2, CCL3, and CCL20." (PMID 33277616, 2020). "Especially in immunogenic tumours, the recruitment of infiltrating regulatory T cells by CCL20 expression should be additionally considered." (PMID 32601464, 2020). "Studies have reported that the CCL20/CCR6 axis plays a key role in the tumor-chemokine network and promotes tumor progression in HCC and CRC." (PMID 31991604, 2020). "A study demonstrated increased expression of chemokine C-C motif ligand 20 (CCL20) by tumor-associated macrophages, which attracts T regs via CCR6 that serves as a receptor for CCL20." (PMID 35582227, 2020). "CCL20 production was verified by immunohistochemistry in different tumour tissues and correlated with clinical data." (PMID 32601464, 2020). "Expression of the chemokine CCL20 in tumours correlates with advanced tumour stage, increased lymph node metastasis and decreased survival in patients." (PMID 32601464, 2020). "Injection of recombinant CCL20 into the tumor site has promoted Treg recruitment and tumor progression in CRC-transplanted mice." (PMID 32707869, 2020). "Tumor cells and tumor cell-derived cell lines in EBV-associated HL were found to have increased expression of the chemokine CCL20, which increased chemotaxis of immunosuppressive CD4+/CD25+ Treg cells in vitro." (PMID 33102204, 2020). "Our qRT-PCR analysis demonstrated significant up-regulation of three tumor-promoting cytokines, Cxcl10, Ccl20, and Tnf and down-regulation of the tumor inhibitory cytokine Il24 in the MDA-F471 spheres relative to parental cells." (PMID 31001473, 2019). "Previous studies indicate that CCL20 has the ability to recruit lymphocytes and has been correlated with tumor progression in various malignant neoplasms." (PMID 31387598, 2019). "Collectively our results suggest that blockade of CCL20 suppresses tumor progression and restores 5-FU sensitivity in CRC, which is mediated by decreased Treg recruitment." (PMID 31395078, 2019). "RNAseq analysis showed that CDK2i- and EZH2i-upregulated genes were enriched in the chemokine/cytokine pathways, such as TNFA, CXCL2, and CCL20, which affect the tumor microenvironment." (PMID 31704972, 2019). "Th9 cells can stimulate epithelial cells by IL-9 to produce CCR6 ligand CCL20, which recruits immature DCs (iDCs) and other APCs into tumor region, and then these APCs present antigen to activate CD8 cytotoxic T lymphocyte (CTLs) to kill tumor cells." (PMID 31414895, 2019). "CCL20 preferentially mediates the recruitment of Th17 cells to tumor tissues, resulting in increased IL-17A secretion." (PMID 31387598, 2019).
tumor (continued). "We found that the level of CCL20 derived from tumor cells was significantly higher in Folfox-resistant patients than in Folfox-sensitive patients." (PMID 31395078, 2019). "CCL20 assists tumor cells in immune evasion by increasing the migration of CD4+Foxp3+ Tregs towards tumor location." (PMID 31192256, 2019). "CCL20 was highly expressed in the cytoplasm of tumor cells, and IL-17A was mainly from infiltrating lymphocytes." (PMID 31387598, 2019). "Th17 cells are recruited to tumor sites and inflammatory sites by C-C motif chemokine ligand 20 (CCL20) expressed by epithelial and stromal cells, interacting with C-C Chemokine receptor type 6 (CCR6) on Th17 cells." (PMID 31921642, 2019). "Lastly, CRC patients who received neoadjuvant chemotherapy with high levels of FOXO1, CEBPB, and CCL20 in tumor tissues showed worse overall survival." (PMID 31395078, 2019). "qRT-PCR results also showed that the expression of FOXP3 and CCL20 mRNA in tumor tissues is greater than in NATs and CCL20 and FOXP3 mRNA expression were significantly correlated." (PMID 31852159, 2019). "F. nucleatum-enriched CRCs demonstrated increased release of C-C motif chemokine ligand 20 (CCL20), stimulation of NF-κΒ signaling, and induction of tumor infiltration through migration of activated macrophages." (PMID 31450675, 2019). "Conditional TAM ablation blocked Treg‐cell recruitment and inhibited tumor growth by decreasing the level of CCL20 in xenografted mice." (PMID 31365790, 2019). "A similar correlation analysis was performed, and a positive correlation was observed between the protein levels of CCL20 and IL-17A in tumor tissues (r = 0.361, p = 0.0025)." (PMID 31387598, 2019). "For these tumor entities, using cell line and xenograft models, a role for CCL20 in cancer development has been established." (PMID 31561620, 2019). "CCL20 and CXCL1 are chemokines mediated by cancer cells or other immune cells in the tumor microenvironment and are associated with the differentiation and progression of ccRCC." (PMID 31747386, 2019). "The inflammatory chemokine ligand 20 (CCL20) and its receptor CCR6 were found to be associated with tumor prognosis in some studies." (PMID 31852159, 2019). "The importance of the iNKT cell-TAM crosstalk is further strengthen in the same model, by showing that iNKT cells are recruited into tumor in a CCL20-dependent manner, but inhibited in their anti-tumor activity by macrophage-induced hypoxia." (PMID 30369933, 2018). "Our results in vivo also showed that CCL20 significantly accelerated tumor growth of MDA-MB-231 xenograft in nude mice." (PMID 30052635, 2018). "Some NPC cases contain CCL20-expressing tumor cells which attract CCR6-expressing Treg cells, as has been shown both in vitro and in vivo." (PMID 29652813, 2018). "Since we have shown that p65 NF-κB mediated the effects of CCL20, therefore, we also investigated the effect of blocking p65 NF-κB activation on the tumor growth." (PMID 30052635, 2018). "In vivo, we testified gene expression in xenograft tumor from control/u50535OE mice model and found that the u50535 overexpression can upregulate CCL20 and its following signal molecules such as CCR6, ERK, AKT, NFKBIA and so on." (PMID 29970882, 2018). "Immunohistochemical analysis demonstrated that CCL20 is strongly and diffusely expressed in tumor cells of the majority of well and poorly differentiated PTC." (PMID 29977225, 2018). "In response to different stimuli including IL-6, TGFβ, CCL20, IL-23, IL-1β, and so on, especially under cancer microenvironments, Th17 cells can mediate tumor regression or tumor promotion." (PMID 29379802, 2017). "CCR9, and CCL20, which are involved in promoting metastasis by enhancing tumor cell proliferation and migration." (PMID 28928458, 2017). "A large body of evidence shows that CCL20 is correlated with tumor formation, metastasis, or progression in various tumors." (PMID 29212174, 2017).
tumor (continued). "The omental tumor tissues from SKCXCR2-bearing mice expressed higher mRNA levels of CCL20 in chemokines and CXCR4 in chemokine receptors compared to those from SKA-bearing mice." (PMID 27723802, 2016). "Accumulating evidence showed that CCL20 was correlated with tumor formation, metastasis or progression in many malignant neoplasms, such as colorectal and breast cancer." (PMID 27015366, 2016). "Chemokine PCR array revealed that CCL20 mRNA levels were significantly increased in SKCXCR2-derived tumor tissues." (PMID 27723802, 2016). "TH9 cells also induce host anti-tumor CD8+CTL responses by upregulating the CCL20/CCR6-dependent recruitment of dendritic cells (DCs) to local tumor tissues." (PMID 27589682, 2016). "The results from our present study suggest that NF-κB is an important signaling for the induction of CCL20 as shown higher activation of NF-κB and expression of CCL20 in SKCXCR2-derived tumor tissues." (PMID 27723802, 2016). "Different from cell culture system where CXCL1 and 2 were enhanced, CCL20 was specifically increased in SKCXCR2-derived tumor tissues compared to SKA-derived tumor tissues." (PMID 27723802, 2016). "Based on higher NF-κB activation and CCL20 expression in the omental tumor tissues from SKCXCR2-bearing mice, we investigated if NF-κB signaling is critical in regulating CCL20 using parental SKOV-3 cells." (PMID 27723802, 2016). "The expression of CCL20, one of the critical chemoattractants responsible for inflammation cells recruitment, has been shown overexpressed in variety of tumours." (PMID 26968871, 2016). "In contrast to the increase of CCL20 in SKCXCR2-derived tumor tissues in vivo, SKCXCR2 cells in vitro had specific increase in CXCL1/2 through NF-κB signaling compared to SKA cells." (PMID 27723802, 2016). "It is suspicious that high concentrations of CCL20 in the lung tumour environment increase tumour progression via attracting those T cells, functioning as an immune escape mechanism." (PMID 26968871, 2016). "From the hypoxically suppressed proinflammatory genes identified by RNA sequencing, four secreted inflammatory factors (CCL20, CXCL5, CSF2 and TNFα) associated with tumor inflammation were chosen for further validation." (PMID 25978030, 2015). "Tumor infiltrating Th17 cells induced CCL20 production, thus promoting DC recruitment within the tumor and subsequent migration to draining lymph nodes of tumor material containing DCs, leading to potential activation of CD8+ T cells." (PMID 26583099, 2015). "In contrast to the IL-17 antitumor activity observed in mice injected with splenocytes, we observed that IFN-gamma, IL-6, IL-23, Ccl2, and Ccl20 proteins were significantly increased in tumor tissues of mice injected with IL-17." (PMID 26684834, 2015). "Intratumoral recruitment of Th17 cells was proposed to rely on various chemokines depending on the tumor context, such as CCL20, CCL17, CCL22, MIF, RANTES, MCP1, or CCL4 produced by immature myeloid cells." (PMID 26583099, 2015). "Cells at the stage of early neoplasia from MMTV-PyMT Ccr6WT mammary glands were assayed for proliferation upon stimulation with CCL20." (PMID 26047945, 2015). "We found significantly higher mRNA expression of CCL20 in the tumor tissues compared to non-tumor tissues and normal control tissues (P < 0.01)." (PMID 25768730, 2015). "Th17 cells also promoted CCL20 chemokine production by tumor tissues, thereby recruiting CD8+ T cells to the malignant site." (PMID 24987392, 2014). "Once the tumor cells have entered the blood or lymphatic vessels, the constitutive expression of CCL20 by the liver or other sites attracts a second wave of CCR6-expressing CRC cell migration." (PMID 24979261, 2014). "CCR6/CCL20 in tumor microenvironments in addition plays a crucial role in driving phenotypic switch of hematopoietic cells with increased potential for angiogenic EC differentiation and attenuated proinflammatory activity." (PMID 25110692, 2014).
tumor (continued). "In a mouse CRC model, CCR6(+) Tregs are recruited into the tumor by responding to CCL20 secreted not only by tumor cells but also by TAMs." (PMID 25110692, 2014). "The Dong group showed that adoptive transfer of tumor-specific Th17 cells resulted in robust activation of tumor-specific cytotoxic T-cells, and the anti-tumor response elicited was dependent on the Th17 cell-mediated production of CCL20." (PMID 26344346, 2013). "SQ injection of irradiated tumor cells expressing CCL20, followed by a second vaccination of DCs pulsed with irradiated tumor cells at the same injection site resulted in significantly more robust tumor rejection than DC vaccine alone." (PMID 24967094, 2013). "The percentage of rectal epithelial cells co-expressing CCL20 and CCR6 was 20.4% of all the patients, including 23.4% (18/77) of patients without neoplasia and 6.3% (1/16) of patients with UC-associated neoplasia." (PMID 24179507, 2013). "In the present study, a high expression level of CCL20 and a low expression level of CCR6 in the rectal mucosa were correlated with the development of UC-associated neoplasia." (PMID 24179507, 2013). "Immunohistochemical analysis for CCL20 and CCR6 expression in the rectal mucosa was performed and the correlation between expression and the pathogenesis of UC-associated neoplasia was investigated." (PMID 24179507, 2013). "CCL20 was recently shown to direct iDC migration and is postulated to play a role in tumor immunotherapy." (PMID 24967094, 2013). "This CCL20 mediated effect is likely to occur via attracting Treg-cells to the tumor mass or directly stimulating CRC cancer cells or both." (PMID 21559338, 2011). "Together, these data indicate that TAMs support the accumulation of CCR6+ tumor-infiltrating Treg-cells, and, at least in part via this mechanism, promote the release of CCL20 in CRC in mice." (PMID 21559338, 2011). "We found that only the mRNA expression of CCL20 was significantly increased in tumor than in non-tumor and normal control tissues (T vs. nT, P<0.001; T vs. NC, P = 0.021)." (PMID 21935436, 2011). "Most importantly, our finding revealed that the administration of recombinant mouse CCL20 led to a marked increase in tumor size in our CRC mouse model." (PMID 21559338, 2011). "We showed that tumor size was significantly increased in mice treated with recombinant mouse CCL20 compared with PBS controls, suggesting a critical role of CCL20 in CRC growth and development." (PMID 21559338, 2011). "To further study the pathological importance of CCL20, we administrated recombinant mouse CCL20 around tumor sites weekly for 4 weeks." (PMID 21559338, 2011). "The administration of recombinant mouse CCL20 resulted in a marked accumulation of CCR6+ Treg-cells in tumor sites as detected by both immunofluorescence staining and an in vivo fluorescence imaging." (PMID 21559338, 2011). "Second, the Tcregs in PBMCs showed high levels of expression of CCR6, a ligand of chemokine CCL20, which is usually overexpressed in the NPC tumor microenvironment and upregulated by the EBV-encoded LMP1 protein." (PMID 22051182, 2011). "Meanwhile, we observed the attraction of tumor cells to FoxP3+ cells by secreting massive CCL20 (right)." (PMID 21935436, 2011). "Injection of recombinant mouse CCL20 into tumor sites promoted its development with a marked recruitment of Treg-cells in the graft CRC model." (PMID 21559338, 2011). "Conditional macrophage ablation decreased CCL20 levels, blocked Treg-cell recruitment and inhibited tumor growth in CD11b-DTR mice grafted with CMT93." (PMID 21559338, 2011). "Three weeks later, we detected the majority of CCL20+ cells (78.98%) was GFP+ CMT93 tumor cells, suggesting most of other CCL20 producing cells are tumor cells." (PMID 21559338, 2011). "Using GFP labeled CMT93, we demonstrated that besides macrophages the majority of CCL20 producing cells in the tumor microenvironment were cancer cells." (PMID 21559338, 2011).
tumor (continued). "In contrast to PBS treatment, we observed that GFP+ Treg-cells were significantly increased within the tumor that was treated with recombinant mouse CCL20." (PMID 21559338, 2011). "First, only the CCR6 ligand CCL20 had elevated expression at both mRNA and protein levels in tumor tissues." (PMID 21935436, 2011). "In order to further confirm GFP labeled Treg-cells migrated to the tumor mass in response to recombinant mouse CCL20, single cell suspensions of tumor tissue were prepared and FoxP3GFP+ Treg-cells were detected by Flow cytomery at the end of the experiment." (PMID 21559338, 2011). "TAMs contributed to the increased CCL20 production in the tumor environment and recruited Treg-cells that expressed high levels of CCR6." (PMID 21559338, 2011). "TAMs recruit CCR6+ Treg-cells to tumor mass and promote its development via enhancing the production of CCL20 in a CRC mouse model." (PMID 21559338, 2011). "We observed large amounts of CCL20-secreting cancer cells and, occasionally, scattered CCL20-secreting Kuffer cells in tumor region (right)." (PMID 21935436, 2011). "We have demonstrated a critical role of CCL20 in the recruitment of Treg-cells into tumor tissue by the injection recombinant mouse CCL20." (PMID 21559338, 2011). "Tumor-infiltrating Th17 cells express high levels of CCR4 and CCR6 and therefore respond to tumor-derived CCL20 signals." (PMID 21197451, 2011). "In the present study, we demonstrated that F4/80-B220-CD11c+ DC precursors mobilized by CCL3 and CCL20 can induce tumor-specific CTL and elicit potent, therapeutic effects against solid and metastatic tumors when modified with MAGE-1." (PMID 20420712, 2010). "In this study, CCL3 and CCL20-recruited DCs were modified with a tumor antigen gene and used as vaccines for an anti-tumor immune response ex vivo and in vivo." (PMID 20420712, 2010). "We further showed that Th17 cells can be induced and expanded in tumour microenvironment through cytokines produced by tumour cells and TILs, and in addition can be recruited to the tumour milieu through a CCR6/CCL20-dependent mechanism." (PMID 20877351, 2010). "In vivo, vaccination with CCL3 and CCL20-recruited DCs modified with MAGE-1 remarkably inhibited subcutaneous tumor growth and size." (PMID 20420712, 2010). "In this treatment model, the benefit of CCL3 and CCL20-recruited DCs as a tumor treatment was quantified by counting metastatic foci in pulmonary tumor-bearing mice." (PMID 20420712, 2010). "Here, we show that the chemokine receptor CXCR4 stimulates the production of the chemokine CCL20 and that CCL20 stimulates the proliferation and adhesion to collagen of various tumor cells." (PMID 19340288, 2009). "Since CCL20 is a potent chemoattractant for immature DCs, the most powerful antigen-presenting cells, it seems logical to attract iDCs to the tumor site to induce antitumor immune response." (PMID 19340288, 2009). "Animals treated with anti-CCL20 antibodies demonstrated a delay in tumor appearance – in the control group on day 28, 100% of animals developed visible tumors, while in the anti-CCL20-treated group, only 60% appeared with tumors on the same day." (PMID 19340288, 2009). "Previous studies have demonstrated that overexpression of chemokines (including CCL-20) in murine tumor cells can induce anti-tumor T-cell responses by recruiting immature dendritic cells." (PMID 16375766, 2005). "This study integrates single-cell RNA sequencing (scRNA-seq) of NPC tissues with validation in 109 primary patient samples, revealing CXCL10 and CCL20 as tumor-secreted chemokines localized to distinct malignant epithelial subpopulations with antagonistic roles." (PMID 41399390, 2026). "In summary, we found that CXCL10 and CCL20 in NPC primarily originate from tumor cells and may represent a pair of antagonistic cytokines." (PMID 41399390, 2026).